NRP1 (neuropilin 1)
Diseases named in the same sentence as NRP1 in open-access papers (continued):
Sharing a sentence is not in itself a finding about the gene and the disease.
ischemia reperfusion injury (1 paper, 2025). Adverse functional, metabolic, or structural changes in ischemic tissues resulting from the restoration of blood flow to the tissue (reperfusion), including swelling; hemorrhage; necrosis; and damage from free radicals. "In the study of ischemia-reperfusion injury in aging kidneys, an increase in the expression of Neuropilin-1 (NRP1) and hypoxia-inducible factor 2a (HIF2a) was observed in endothelial cells (ECs)." (PMID 39781471, 2025).
ischemic disease (1 paper, 2025). Lack of blood supply to an area of the body, resulting in impairment of tissue oxygenation. "In conclusion, our study identifies L-theanine as a promising candidate for the treatment of ischemic diseases, demonstrating a novel mechanism of action through modulation of the NRP1/VEGFR2 pathway." (PMID 39803888, 2025).
kidney injury (1 paper, 2024). Trauma to the kidney. "We observed upregulation of NRP1 in distal TECs from kidney transplant recipients with renal dysfunction and mice with I-R-induced kidney injury." (PMID 38977708, 2024).
laryngeal carcinoma (1 paper, 2013). Carcinoma that arises from the laryngeal epithelium. "NRP-1 was studied in laryngeal carcinoma and found to be expressed in laryngeal squamous cell carcinoma tissues by IHC and all laryngeal cell lines by RT-PCR." (PMID 23563900, 2013).
Listeria infection (1 paper, 2014). "However, the same was true for Nrp1-deficient T cells, suggesting Nrp1 was not involved in the regulation of effector cytokine production by tolerant CD8+ T cells, nor was Nrp1 required for self-reactive CD8+ T cells to acquire effector functions during Listeria infection." (PMID 25343644, 2014).
lymphedema (1 paper, 2020). Excess fluid collection in tissues, causing swelling. "Regarding variants in the NRP1 gene, the first proband, male, 68 years, has had lymphedema of the lower limbs since his youth." (PMID 33212964, 2020). "Although further functional and biochemical studies are needed to clarify their involvement with lymphedema and to associate NRP1 and NRP2 with lymphedema, we suggest that it is worthwhile also screening lymphedema patients for these two new candidate genes." (PMID 33212964, 2020). "A segregation analysis in familial lymphedema cases added evidence that NRP1 and NRP2 qualify as candidate genes to include in the genetic testing of lymphedema patients." (PMID 33212964, 2020). "Given their functional role and our findings, we suggest that NRP1 and NRP2 should be considered candidate genes for inclusion in the gene panel for genetic testing of lymphedema patients." (PMID 33212964, 2020). "In our study, a cohort of 235 Italian lymphedema patients, who tested negative for variants in known lymphedema-associated genes, was screened by a next-generation sequencing (NGS)-targeted panel for variants the in NRP1 and NRP2 genes." (PMID 33212964, 2020).
memory impairment (1 paper, 2024). "Intriguingly, we showed that overexpression of hippocampal Nrp1 rescued Dnmt3a1 knockdown-dependent memory impairments." (PMID 38499720, 2024). "Taken together, these results demonstrate that Nrp1 acts downstream of Dnmt3a1, is required for memory formation and can per se rescue Dnmt3a1-dependent memory impairments." (PMID 38499720, 2024).
mesothelioma (1 paper, 2013). A usually malignant and aggressive neoplasm of the mesothelium which is often associated with exposure to asbestos. "It has been shown that the expression of VEGFR-1/Flt-1, VEGFR-2/KDR, Nrp-1 and Nrp-2 remains unchanged during the malignant transformation of MCs (e.g. mesothelioma)." (PMID 23585849, 2013).
metastasis (1 paper, 2023). The spread or migration of cancer cells from one part of the body (where they first appeared) to another. "Thus, expression of NRP1 is significantly higher in CD3-positive and CD4-positive tumor-infiltrating lymphocytes (TILs) compared to peripheral blood mononuclear cells (PBMCs) in patients with CRC liver metastasis." (PMID 37894289, 2023).
myoblastoma (1 paper, 2025). "In myoblastoma (MB), overexpression of NRP1 plays a key role in the survival of CSCs, inhibiting the NRP1 via a peptidomimetic specifically targeting the protein by losing their stemness characteristics, thereby decreasing the invasiveness capacity of MB CSCs." (PMID 40277760, 2025).
ovarian endometrioid carcinoma (1 paper, 2011). "Based on preliminary immuno-screening results, we investigated in detail the expression of Sema3E and its receptors, Plexin-D1 and Neuropilin-1 (Npn1), in human ovarian endometrioid carcinomas." (PMID 21559368, 2011).
Pain (1 paper, 2020). An unpleasant sensory and emotional experience associated with actual or potential tissue damage, or described in terms of such damage. "In chronic neuropathic pain, a concomitant increase of NRP-1 and VEGF-A have been reported in DRG neurons." (PMID 32869019, 2020). "Spike protein and inhibition of NRP-1 confer anti-nociception in the spared nerve injury model (SNI) of chronic neuropathic pain." (PMID 32869019, 2020).
pancreatic neuroendocrine tumor (1 paper, 2022). Pancreatic endocrine tumor, also known as pancreatic neuroendocrine tumor (PNET), describes a group of endocrine tumors originating in the pancreas that are usually indolent and benign, but may have the potential to be malignant. "Related studies suggest that NRP-1 may be regulated by STAT3, and that NRP-1 is upregulated in pancreatic neuroendocrine tumor tissues and correlates with the metastatic ability of pancreatic neuroendocrine tumor cells." (PMID 36105933, 2022).
paraganglioma (1 paper, 2022). A benign or malignant neoplasm arising from paraganglia located along the sympathetic or parasympathetic nerves. "Analysis in TIMER2.0 revealed that NRP1 was significantly differentially expressed across the six immune subtypes in LGG (p = 2.19e-18), BRCA (p = 3.62e-11), KIRC (p = 1.81e-09), pheochromocytoma/paraganglioma (PCPG) (p = 1.53e-06), LUSC (p = 2.36e-06), COAD (p = 9.13e-06), and STAD (p = 1.57e-05)." (PMID 36338984, 2022).
parasitemia (1 paper, 2023). "Brain weight, an initial indicator for brain edema and neuroinflammation, was significantly reduced upon deletion of Nrp-1 expression on T cells during PbA infection, whereas blood parasitemia was comparable between the groups." (PMID 38019895, 2023).
Peritoneal Fibrosis (1 paper, 2013). Disorder characterized by a wide range of structural changes in PERITONEUM, resulting from fibrogenic or inflammatory processes. "In contrast, peritoneal biopsies from PD patients, with evident signs of peritoneal fibrosis, showed up-regulated expression of Nrp-1 in spindle-like cells embedded in the fibrotic stroma, located mainly in the upper submesothelial area." (PMID 23585849, 2013).
persistent truncus arteriosus (1 paper, 2021). A rare congenital cardiovascular disorder characterized by the failure of the embryologic structure truncus arteriosus to divide into the aorta and pulmonary trunk. "In contrast to the neuropilin-1 variants that lack the MAM domain and supporting neuropilin-1′s role in mediating a switch between VEGF and semaphorin signaling, a splice site mutation that leads to a truncated neuropilin-1 has been linked to persistent truncus arteriosus." (PMID 34436232, 2021).
pituitary tumours (1 paper, 2008). "Oestrogen-induced rat pituitary tumours and GH3 pituitary tumour cells express VEGF164 and coreceptor, neuropilin-1." (PMID 18081553, 2008).
plasma cell neoplasm (1 paper, 2023). A clonal proliferation of immunoglobulin-secreting plasma cells. "Nevertheless, NRP‐1/CD304 was not positive in other hematolymphoid neoplasms (T‐ALL, B‐NHL, T/NK‐cell lymphoma, and plasma cell neoplasms)." (PMID 36965095, 2023). "However, there are no comprehensive and detailed reports on the expression of NRP‐1/CD304 in other common hematological diseases besides BPDCN, AML, and B‐ALL, such as T‐ALL, B‐NHL, T/NK‐cell lymphoma, and plasma cell neoplasms." (PMID 36965095, 2023).
plasmacytoma (1 paper, 2025). Plasmacytoma is a localized mass of neoplastic monoclonal plasma cells that represents approximately 5% of all plasma cell neoplasms. "Long non-coding RNA plasmacytoma variant translocation (PVT1) binds to NRP1 and regulates its expression but knock down of PVT1 suppresses the growth and metastasis of Circulating Endothelial cells (CEC), explaining the role of NRP1." (PMID 40277760, 2025).
primary immunodeficiency (1 paper, 2023). "Specifically, NRP1 was significantly associated with primary immunodeficiency, myeloid leukocyte migration, interleukin interactions, and inflammatory response regulation." (PMID 37190154, 2023). "NRP1 is involved in primary immunodeficiency, hematopoietic cell lineage regulation, and myeloid leukocyte migration, which may explain the positive correlation between NRP1 expression and myeloid immune cell infiltration." (PMID 37190154, 2023).
promyelocytic leukemia (1 paper, 2025). "Our results demonstrate that HGF increases NRP-1 expression by activating the transcription factor RARA, which is a component of the promyelocytic leukemia/RARA oncoprotein." (PMID 40419692, 2025).
Pulmonary hemorrhage (1 paper, 2019). Pulmonary hemorrhage is a bleeding within the lungs. "Induction of early postnatal SMC-specific Nrp1 knockout led to pulmonary hemorrhage associated with defects in alveogenesis and revealed a specific requirement for Nrp1 in myofibroblast recruitment to the alveolar septae and PDGF-AA-induced migration in vitro." (PMID 30649916, 2019).
Renal insufficiency (1 paper, 2024). A reduction in the level of performance of the kidneys in areas of function comprising the concentration of urine, removal of wastes, the maintenance of electrolyte balance, homeostasis of blood pressure, and calcium metabolism. "Here, we show that NRP1 is upregulated in distal tubular (DT) cells of patients with transplant renal insufficiency and mice with renal ischemia-reperfusion (I-R) injury." (PMID 38977708, 2024).
reovirus infection (1 paper, 2025). "The precise functions of PirB and NRP1 in reovirus infection of CNS neurons are not known, but it is possible that they contribute to infection at different sites in the brain or mediate independent steps in the reovirus entry pathway." (PMID 39932305, 2025).
retinal diseases (1 paper, 2021). "Hence, it has been suggested that NRP-1 may be responsible for retinal diseases and conditions." (PMID 34202613, 2021).
SARS-CoV infection (1 paper, 2023). "For example, among the mRNAs downregulated with SARS-CoV-2 infection (but not with SARS-CoV infection), SEMA3C is a theoretically calculated target of multiple upregulated tRFs and a ligand of NRP1, a SARS-CoV-2 receptor." (PMID 38203569, 2023).
schizophrenia (1 paper, 2025). A major psychotic disorder characterized by abnormalities in the perception or expression of reality. "The HSV-1 interactome shows specific enrichment in genome-wide association studies of schizophrenia, with particular viral entry receptors such as the neuropilin-1 (NRP1) receptor appearing in schizophrenia datasets." (PMID 40806558, 2025).
schwannoma (1 paper, 2017). A benign, usually encapsulated slow growing tumor composed of Schwann cells. "Primary human VSs and an established schwannoma cell line both express αv integrins and neuropilin-1 on the cell surface, two receptors that serve as “zip codes” for the targeting peptide ligand iRGD." (PMID 29018206, 2017).
small cell carcinoma (1 paper, 2016). A neuroendocrine carcinoma composed of small malignant cells which are often said to resemble "oat cells" under the microscope. "The frequencies of NRP-1- and NRP-2-positive alveolar macrophages adjacent to small cell carcinomas (n = 3) were also significantly higher than the frequencies of NRP-1- and NRP-2-positive alveolar macrophages in inflamed lung and lung tissue remote to the cancer nest." (PMID 26900851, 2016).
small fiber neuropathy (1 paper, 2016). "This study indicates that capsaicin application results in significant loss of epidermal NRP-1 receptor expression, whereas diabetic subjects presenting small fiber neuropathy show full epidermal NRP-1 expression in contrast to the basal expression pattern seen in healthy controls." (PMID 27598321, 2016).
systemic sclerosis (1 paper, 2025). A chronic disorder, possibly autoimmune, marked by excessive production of collagen which results in hardening and thickening of body tissues. "Consistent with our findings, NRP1 has also emerged as a circulating biomarker of systemic sclerosis-associated PH." (PMID 41402732, 2025).
Thrombocytopenia (1 paper, 2020). A reduction in the number of circulating thrombocytes. "A recent phase Ib study showed that the anti-NRP-1 mAb MNRP1685A elicited thrombocytopenia." (PMID 33266104, 2020).
thrombosis (1 paper, 2024). "Among them, mutations in ABCA13, FLT1, NRP1, SWAP70 and SLC15A4 are strongly associated with immunity or proliferation, whereas mutations in VWF, SELP and EPHB2 are associated mainly with thrombosis." (PMID 39671267, 2024).
tongue cancer (1 paper, 2012). A malignant neoplasm affecting the tongue. "In our study, NRP1 was poorly expressed in normal oral epithelium but was extensively up-regulated in tongue cancer tissue." (PMID 22926477, 2012). "In conclusion, in this study, we observed the over-expression of NRP1 and loss of SEMA3A expression in human tongue cancer." (PMID 22926477, 2012). "Statistical analyses were performed using Chi-squared and Spearman tests and Kaplan-Meier analysis.Results: SEMA3A was significantly down-regulated in tongue cancer compared with normal tongue (P=0.025), while NRP1 was over-expressed in tumours (P<0.001)." (PMID 22926477, 2012). "Therefore, we focused on the expression of SEMA3A and its receptor NRP1 in tongue cancer and the potential contribution of these molecules in the prediction of prognosis." (PMID 22926477, 2012). "Scores for the NRP1/SEMA3A ratio of ≥1 predicted shorter survival (P=0.045).Conclusions: Aberrant expression of SEMA3A and its receptor NRP1 might be involved in the development of tongue cancer and might be useful prognostic markers in this tumour type." (PMID 22926477, 2012).
tropical spastic paraparesis (1 paper, 2013). "HTLV-1 infects hCMEC/D3 cells via their receptors for viral entry, Glut-1 and neuropilin-1, an observation that has been confirmed in situ in necropsy material from patients with TSP/HAM (tropical spastic paraparesis/human T-lymphotropic virus type-I-associated myelopathy)." (PMID 23531482, 2013).
Usher syndrome (1 paper, 2012). A syndromic diseae characterized by the association of sensorineural deafness (usually congenital) with retinitis pigmentosa and progressive vision loss. "Several of the top candidate genes include EEF1A1, ROBO1, PLXNA4, SLIT3, NRP1, and NOTCH2, as well as genes associated with the Usher syndrome, PCDH15 and USH2A, and are plausible candidates contributing to the developmental defects in Gbx2−/− mice." (PMID 23144817, 2012).
Ventricular arrhythmia (1 paper, 2022). "However, previous studies also indicated that induction of ventricular arrhythmias is a severe side effect preventing the use of VEGF-B186 in cardiac gene therapy, possibly mediated by binding to neuropilin 1 (NRP1)." (PMID 35992336, 2022).
Vestibular schwannoma (1 paper, 2017). A vestibular schwannoma (also known as acoustic neuroma, acoustic neurinoma, or acoustic neurilemoma) is a benign, usually slow-growing tumor that develops from the VIIIth cranial nerve supplying the inner ear. "The peptide selectively binds to integrins on vestibular schwannoma cells via the RGD sequence, undergoes proteolytic processing and interacts with NRP-1 via the CendR motif to trigger cellular internalization and tissue penetration." (PMID 29018206, 2017).
tumor (873 papers, 2003 to 2026). "Another finding of this study was the expression of NRP1 in the endothelium of tumor vessels, which showed a diffuse pattern and was associated with the formation of aberrant vessels without perivascular astrocytic end feet." (PMID 40805120, 2025). "Increased NRP1 expression is associated with tumor angiogenesis, advanced tumor–node-metastasis, pT stage, node invasion, and dismal postoperative survival." (PMID 40277760, 2025). "NRP1 is expressed in tumor-associated vessels and various cancers, indicating a role in tumor progression." (PMID 40277760, 2025). "Gain and loss of function experiments determined the role of NRP1 in tumor progression using The Cancer Genome Atlas (TCGA) database in vascular endothelial cells." (PMID 40277760, 2025). "In the present study, we report for the first time the expression of NRP1 in tumor-associated microglia/macrophages (TAMs) within the MB microenvironment." (PMID 40805120, 2025). "In the context of cancer, NRP1 has been implicated in several key processes that contribute to tumor progression." (PMID 40277760, 2025). "Previous studies documented NRP1 expression in MB tumor cells and its association with angiogenesis and tumor progression." (PMID 40805120, 2025). "The penetration cascade continues within the extravascular tumor tissue mediated by cells that express αv integrins and NRP-1, such as cancer-associated fibroblasts (CAFs) and cancer epithelial cells." (PMID 40892758, 2025). "Tregs with Nrp1 deficiency are known to lose their ability to inhibit the tumor immune microenvironment, which means that Nrp1 deficiency enhances antitumor activity." (PMID 40216744, 2025). "Nevertheless, the reproducibility of these trends across subgroups supports a biologically meaningful association between NRP1 expression and tumor progression, angiogenesis, and immunomodulation." (PMID 40805120, 2025). "Pathways: NRP1 has been implicated in regulating key metabolic pathways that support tumor growth, such as glycolysis and lipid metabolism." (PMID 40277760, 2025). "In vivo studies have proven that the loss of NRP-1 leads to decreased perfusion and tumor size, which is correlated with a decrease in the intensity of the EndMT process and fibrosis." (PMID 40430075, 2025). "High NRP1 expression is frequently associated with aggressive tumor phenotypes and poor patient outcomes." (PMID 40277760, 2025). "High levels of NRP-1 have been linked with a more aggressive tumor cell phenotype, suggesting its potential importance as an indicator of disease progression." (PMID 40430075, 2025). "Previous studies have shown that NRP1 is closely associated with tumor progression and metastasis and is significantly linked to poorer patient survival in CRC." (PMID 40257955, 2025). "The current study presents evidence of the differential impact of substrate stiffness on two tumoral and two non-tumoral cell lines, concerning the regulation of cell morphology, migration, and NRP1 expression, a protein associated with tumor progression." (PMID 38903533, 2024). "Neuropilin‐1 (NRP1) is an immune checkpoint that inhibits Tpex cell self‐renewal, and mice with NRP1‐deficient CD8+ T cells were protected against tumour rechallenge and showed an enhanced response to anti‐PD1 immunotherapy." (PMID 39169517, 2024). "Among the proteins implicated in cancer progression, the neuropilin-1 receptor (NRP1) has been linked to facilitating tumor proliferation, invasion, migration, and EMT." (PMID 38903533, 2024). "In the macrophage, NRP1 is localized to the cell membrane and regulates M2 polarization and tumor-associated macrophage function." (PMID 39684750, 2024). "NRP1 plays a crucial role in entering TAMs into hypoxic niches; meanwhile, loss of NRP1 restores anti-tumor immunity and inhibits angiogenesis." (PMID 36260158, 2023). "In cervical cancer, NRP1 is critical for the activation of tumor-associated macrophages by a hypoxic tumor microenvironment." (PMID 37894289, 2023).